RNU6-853P (RNA, U6 small nuclear 853, pseudogene)
Gene: Small nuclear RNA gene on chromosome 4 (168,885,355 to 168,885,461, forward strand). Ensembl gene ENSG00000201176.
Homologues: Orthologues: chimpanzee U6 (95% identical), macaque U6 (93% identical), guinea pig U6 (80% identical), rat U6 (79% identical). Paralogues in human: RNU6-1181P (85% identical), RNU6-1024P (84% identical), RNU6-1316P (84% identical), RNU6-1324P (84% identical), RNU6-589P (84% identical), RNU6-60P (84% identical), RNU6-737P (84% identical), RNU6-905P (84% identical), RNU6-106P (83% identical), RNU6-1145P (83% identical), RNU6-1241P (83% identical), RNU6-12P (83% identical), and 1284 more.